NUMB (NUMB endocytic adaptor protein)
Description:
Regulates clathrin-mediated receptor endocytosis. Plays a role in the process of neurogenesis (By similarity). Required throughout embryonic neurogenesis to maintain neural progenitor cells, also called radial glial cells (RGCs), by allowing their daughter cells to choose progenitor over neuronal cell fate (By similarity). Not required for the proliferation of neural progenitor cells before the onset of neurogenesis. Also involved postnatally in the subventricular zone (SVZ) neurogenesis by regulating SVZ neuroblasts survival and ependymal wall integrity (By similarity). May also mediate local repair of brain ventricular wall damage (By similarity).
Synonyms: C14orf41; S171; c14_5527; LOC101928143
Tractability: Antibody: UniProt places it where antibodies can reach, with high confidence; its Gene Ontology location is reachable by antibodies, with high confidence; the Human Protein Atlas places it where antibodies can reach. PROTAC: UniProt records ubiquitination sites on it; ubiquitination databases record sites on it; its protein half-life has been measured.
Gene: Protein-coding gene on chromosome 14 (73,274,146 to 73,466,167, reverse strand). Ensembl gene ENSG00000133961.
Subcellular location: Cell membrane; Endosome membrane
Subcellular location (Human Protein Atlas): Cell Junctions; Cytosol; Plasma membrane
Pathways (Reactome):
Signal Transduction: Activated NOTCH1 Transmits Signal to the Nucleus; Degradation of GLI1 by the proteasome; Hedgehog 'on' state
Developmental Biology: Differentiation of Keratinocytes in Interfollicular Epidermis in Mammalian Skin; Recycling pathway of L1
Gene Ontology:
Molecular function: cadherin binding; protein binding; alpha-catenin binding; beta-catenin binding
Biological process: negative regulation of protein localization to plasma membrane; positive regulation of cell migration; regulation of endocytosis; lateral ventricle development; neuroblast division in subventricular zone; positive regulation of neurogenesis; regulation of postsynaptic neurotransmitter receptor internalization
Cellular component: clathrin-coated vesicle; endosome membrane; focal adhesion; plasma membrane; basolateral plasma membrane; cytoplasm; cytoplasmic vesicle; apical part of cell; clathrin-coated pit; early endosome; glutamatergic synapse
Genetic constraint (gnomAD): Loss-of-function variants: 23 observed, 50.41 expected, observed/expected ratio (o/e) 0.46, 90% interval 0.33 to 0.65. The upper end of that interval is the gene's LOEUF score, 0.65, which puts it in group 2 of 6, group 1 being the genes least tolerant of losing a copy. Missense variants: 660 observed, 779.45 expected, observed/expected ratio (o/e) 0.85, 90% interval 0.79 to 0.9. Synonymous variants: 270 observed, 278.58 expected, observed/expected ratio (o/e) 0.97, 90% interval 0.88 to 1.07.
Homologues: Orthologues: chimpanzee NUMB (99% identical), macaque NUMB (99% identical), dog NUMB (96% identical), pig NUMB (94% identical), mouse Numb (94% identical), guinea pig NUMB (93% identical), rat Numb (93% identical), rabbit NUMB (88% identical), zebrafish numb (65% identical), tropical clawed frog numb (60% identical), Drosophila melanogaster numb (34% identical), Caenorhabditis elegans num-1 (29% identical), and 2 more. Paralogues in human: NUMBL (52% identical), DAB2 (19% identical), DAB1 (16% identical), NOS1AP (12% identical), LDLRAP1 (11% identical), FAM43A (9% identical), MAPK8IP1 (9% identical), MAPK8IP2 (9% identical), FAM43B (7% identical), GULP1 (5% identical), C1orf226 (3% identical).
Diseases named in the same sentence as NUMB in open-access papers:
NUMB is named in the same sentence as 93 diseases in open-access papers, as found by Europe PMC text mining. Sharing a sentence is not in itself a finding about the gene and the disease. The quoted sentences say what the papers report.
breast cancer (36 papers, 2013 to 2025). A primary or metastatic malignant neoplasm involving the breast. "Knockdown of either, or both TDP43 and SRSF3 using shRNA in MDA-MB-231 breast cancer cell lines increased NUMB exon 9 skipping and was associated with reduced proliferation." (PMID 39863103, 2025). "In breast cancer (BC), NUMB loss of function (LOF), mediated by various molecular mechanisms, is a frequent and causal event." (PMID 40411418, 2025). "In breast cancer (BC), NUMB loss of function (LOF) is common and mainly driven by protein hyper‐degradation." (PMID 40411418, 2025). "The silencing of NUMB in primary normal breast cells results in a significant increase in Hes-1 mRNA, and the aberrant activation of Notch signaling in human breast cancers was thought to be due to the loss of NUMB expression." (PMID 35457181, 2022). "The link of NUMB to a cancer stem cell phenotype was demonstrated, and the loss of NUMB expression is a marker of tumor aggressiveness in primary breast cancer." (PMID 35478938, 2022). "For example previous reports have identified somatic mutations of NUMB in breast carcinoma and of PARK2 in GBM, colon, and lung cancers." (PMID 23372550, 2013). "PTBP1, a member of the heterogenous nuclear ribonucleoprotein family is overexpressed in a number of cancers including glioma, ovarian cancer, breast cancer, and colon adenocarcinoma, and promotes the expression of several protein isoforms associated with tumorigenesis including NUMB Ex9in." (PMID 39863103, 2025). "Sequences of KRT19 mRNA in colon and breast cancers show one silent mutation in breast cancer only, which might influence NUMB transcriptional activity." (PMID 30650643, 2019). "NUMB loss or low expression is frequently detected in breast cancer." (PMID 27506933, 2016). "Moreover, loss of NUMB expression can confer a proliferative advantage on breast cancer and non-small cell lung cancer by antagonizing Notch." (PMID 27506933, 2016). "In breast cancer, loss of NUMB expression results from increased proteasomal degradation." (PMID 23771628, 2014). "Moreover, Kaplan-Meier survival analysis revealed that high NUMB expression was associated with decreased distant disease-free survival (DDFS p = 0.0138) of breast cancer patients (left), while high Notch1 expression was associated with increased DDFS (p = 0.0035) of breast cancer patients (middle)." (PMID 27506933, 2016). "Inhibition of MEK1/2 reduces NUMB exon 9 inclusion in lung and breast cancer cell lines while, expression of constitutively active MEK1 or V12-HRAS, causes increased exon 9 inclusion." (PMID 39863103, 2025). "Treatment of breast cancer cells with 10 nmol/L BFT-1 significantly downregulated NUMB and increased NICD1 levels in NOD1-overexpressing cells." (PMID 38437016, 2024). "Compared with PR+ breast cancer, the mRNA levels of UBE2S and UBE2C were higher, while NUMB was lower in PR− breast cancer." (PMID 36860312, 2023). "We subsequently performed a recovery validation assay for NUMB overexpression in exosome-treated breast cancer cells." (PMID 35478938, 2022). "NUMB overexpressed lentivirus supplementation markedly suppressed cell migration, invasion, and proliferation of breast cancer cells compared with exosome group." (PMID 35478938, 2022). "This well-documented NUMB isoform switch was also detected with DJExpress, which showed a ∼16-fold (log2 ∼4-fold) upregulation of NUMB exon 12 inclusion junctions in breast cancer cell lines compared to fibroblasts." (PMID 36304260, 2022).
breast cancer (continued). "It has been reported that NUMB can be downregulated in malignant pleural mesothelioma, salivary adenocarcinoma, breast cancer, esophageal squamous cell carcinoma, and nonsmall cell lung cancer." (PMID 35478938, 2022). "NOTCH1, NOTCH3, and JAG1 expression are associated with poor survival in breast cancer patients, and NOTCH overexpression transformed MCF10A breast cells whilst overexpression of NUMB reversed this transformation." (PMID 36012147, 2022). "The NUMB endocytic adaptor (NUMB) protein is of great significance in the occurrence and development of breast cancer." (PMID 35478938, 2022). "The limitation of this study is that it failed to further verify the regulation of breast cancer cell exosomes on breast cancer and the regulation of NUMB protein expression at the animal level." (PMID 35478938, 2022). "Meanwhile, Western blot and qPCR were conducted to determine the regulation of NUMB expression by exosomes in breast cancer cells." (PMID 35478938, 2022). "NUMB overexpressed lentivirus and control null virus were added into exosomal-treated breast cancer cells to effectively restore the inhibitory effect of exosomes on NUMB expression." (PMID 35478938, 2022). "Total NUMB protein expression was significantly decreased in breast cancer cells treated with exosomes, whereas cell migration and invasion were increased." (PMID 35478938, 2022). "It was also shown that miR-146a is important for the maintenance of breast cancer stem cells during the epithelial–mesenchymal transition (EMT) by suppressing the expression of the Notch signalling inhibitor NUMB." (PMID 33806327, 2021). "Rencently, KRT19 was found to interact with β-catenin/RAC1 complex and regulated NUMB and Notch1 expression, leading to the enhancement of the cancer stem-like cell properties in breast cancer." (PMID 33442422, 2021). "We found that the effect of KRT19 knockdown on Wnt/β-catenin signaling target genes was quite similar except for NUMB expression in both colon and breast cancer cells." (PMID 30650643, 2019). "In breast cancer, NUMB has been defined as a tumor suppressor protein; nevertheless, its role in ICC is not clear." (PMID 29721172, 2018). "In a cohort of breast cancer patients receiving adjuvant chemotherapy, NUMB, and indirectly Notch activation, were inversely correlated with clinical and pathological parameters indicative aggressive disease progression." (PMID 30515368, 2018). "In our previous study, we revealed the role of KRT19 as signaling component which mediated Wnt/NOTCH crosstalk through NUMB transcription in breast cancer." (PMID 29747452, 2018). "In this study, we showed that the expression of miR-129 and NUMB were negatively correlated with the proportion of stem cells in tissues of breast cancer." (PMID 29262559, 2017). "Taken together, these findings demonstrate the inhibitory effects of NUMB in breast cancer progression and metastasis." (PMID 27506933, 2016). "To investigate the pathological significance of NUMB-mediated EMT in breast cancer development and progression, we examined the NUMB expression levels in various breast cancer cell lines." (PMID 27506933, 2016).
breast cancer (continued). "NUMB overexpression resulted in a dramatic reduction in tumor volume, suggesting that NUMB significantly decreased tumor incidence and growth in the breast cancer xenograft model." (PMID 27506933, 2016). "To further investigate the clinicopathological relevance of the NUMB/Notch axis in breast cancer progression, we expanded our observations using publicly available mRNA profiling datasets of breast cancer patients." (PMID 27506933, 2016). "The results showed that NUMB protein levels were lower in the subset of breast cancer samples with poor prognostic parameters, such as ER-negative (p < 0.001), HER2-positive (p = 0.016) and triple-negative (p = 0.023) phenotypes." (PMID 27506933, 2016). "Kaplan-Meier survival analysis showed that inverse Notch1/NUMB expression is a strong predictor of DDFS in breast cancer." (PMID 27506933, 2016). "The results showed that the bioluminescence signal in the lung was strikingly decreased in the mice injected with NUMB-expressing cells, indicating that NUMB negatively regulated the metastasis of breast cancer cells to the lung." (PMID 27506933, 2016). "We respectively evaluated the expression of NUMB and Notch1 in different breast cancer subtypes, ER status and tumor grade." (PMID 27506933, 2016). "Kaplan-Meier survival analysis using the publicly available datasets demonstrated that higher NUMB expression was associated with a better overall survival (OS, p = 0.036) and disease-free survival (DFS, p = 0.028) of breast cancer patients." (PMID 27506933, 2016). "In breast cancers, NUMB protein levels are frequently reduced or lost and inversely correlate with tumor grade and patient prognosis." (PMID 23771628, 2014). "Increased inclusion of NUMB exon 12 has been reported in several types of cancer including lung, ovarian, and breast cancers." (PMID 24722255, 2014). "Recent studies have identified NUMB as a tumor suppressor that is frequently downregulated in breast cancer and non-small cell lung cancer, however, little is known about the clinicopathological significance of NUMB in ESCC." (PMID 24980814, 2014). "Although NUMB abolishes expression of the NOTCH oncogene in breast cancers, which results in tumor suppression in breast cancers, this cannot be the case in HNSCC since NOTCH acts as tumor suppressor in HNSCC rather than as an oncogene." (PMID 24302991, 2013). "A recent report has indicated that TNFα-induced FoxA2 phosphorylation is responsible for the down-regulation of NUMB, which then facilitates breast cancer tumorigenesis by enhancing NOTCH." (PMID 24302991, 2013). "To determine whether this effect also occurs in other cancer types, we detected the phosphorylation of NUMB and PKCζ in cell lines of breast cancer and cervical cancer which overexpress MUC1." (PMID 40349179, 2025). "The relevance of NUMB is also evaluated in the RAB4A-low, NUMB-high MCF7 breast cancer cells." (PMID 39463384, 2024). "We therefore explored whether GAK regulated NUMB by phosphorylation in NOD1-overexpressing breast cancer cells." (PMID 38437016, 2024). "NUMB overexpression markedly declined EDU positive cell ratio in breast cancer cells compared to the exosome group (empty virus), suggesting that NUMB could suppress the proliferation of breast cancer cells." (PMID 35478938, 2022).
breast cancer (continued). "Meanwhile, it also demonstrated that exosomes could reduce NUMB expression levels in breast cancer cells." (PMID 35478938, 2022). "NUMB overexpressed lentivirus could effectively reduce the invasion, migration, and proliferation of breast cancer cells." (PMID 35478938, 2022). "Consistent with our results, high levels of p65/p66 isoforms were reported to be expressed during BRCA1 depletion-driven EMT and two human basal-like breast cancer cell lines, further underscoring the importance of NUMB p65/p66 isoforms in mammary epithelial cells tumorigenesis." (PMID 35457181, 2022). "Taken together, the exosomes of breast cancer cells could inhibit the expression of NUMB and promote the migration, invasion, and cell clone formation of breast cancer cells." (PMID 35478938, 2022). "The breast cancer cell-derived exosomes could enter into breast cancer cells through integration and inhibit the NUMB expression, promote cell migration, invasion, and formation of cell clones in MDA-MB-231 breast cancer cell line." (PMID 35478938, 2022). "Furthermore, at 48 h after rescuing DKK3 or NUMB expression, sphere formation assays and western blot analysis showed that the effect of chemotherapy-elicited exosomes on breast cancer stemness was rescued (p < 0.0001)." (PMID 33823894, 2021). "Furthermore, after transfection with miR-378 mimics and the DKK3 or NUMB overexpression plasmids, western blot analysis showed that the effect of miR-378a-3p and miR-378d on breast cancer stemness was rescued." (PMID 33823894, 2021). "In addition, we found that miR-378 expression was negatively correlated with DKK3 and NUMB expression in breast cancer based on the TCGA database (n = 470) (p < 0.001)." (PMID 33823894, 2021). "Finally, we provide a schematic representation of the biological role of the trans-cellular signaling pathway involving EZH2, STAT3, exo-miR-378a-3p, exo-miR-378d, DKK3 and NUMB in the regulation of breast cancer chemoresistance." (PMID 33823894, 2021). "As NUMB works an upstream inhibitor of the Notch signaling pathway, we also examined expression of Notch signaling-related genes in colon and breast cancer cells." (PMID 30650643, 2019). "Mechanistically, in our previous study, we also found that KRT19 interacted with the β-catenin/RAC1 complex in breast cancer and was subsequently imported into the NUMB promoter in the nucleus, consequently regulating cancer properties through the Notch signaling pathway." (PMID 30650643, 2019). "Our previous study demonstrated that KRT19 could attenuate ALDH1high/CXCR4high/CD133high breast cancer stem cell-like cells (CSLCs) properties by regulating NUMB-mediated wnt/notch signaling crosstalk." (PMID 29747452, 2018). "Specifically, NUMB has been described as an oncosuppressor in breast cancer, esophageal squamous cell carcinoma and mesothelioma, but evidence showed also a role for NUMB as an oncogene in hepatocellular carcinoma, in astrocytomas in cervical squamous carcinoma cells, and in endometrial cancer." (PMID 30443541, 2018). "Considering the in vitro and in vivo data, we investigated whether NUMB expression is clinically correlated with human breast cancer progression." (PMID 27506933, 2016). "In contrast to the low expression of NUMB in BLBC and ER-negative breast cancer patients, Notch1 had a relatively high expression in these breast cancer patients, demonstrating an apparent opposite trend for the expression of NUMB and Notch1 in breast cancers (lower left and middle)." (PMID 27506933, 2016). "In addition, a pan-cancer analysis of NUMB exon 9 inclusion utilizing TCGA RNA-sequencing data confirmed these prior studies and also reported upregulation of NUMB exon 9 across breast cancer subtypes as well as in ovarian, prostate, and testicular cancer (Zhang, 2022 #1146)." (PMID 39863103, 2025).